INS (insulin)
Diseases named in the same sentence as INS in open-access papers (continued):
Sharing a sentence is not in itself a finding about the gene and the disease.
Insulin resistance (continued). "ZnSO4 treatment showed dose-dependent improvements, with the 100 mg/kg dose showing superior effects in reducing glucose (-56.29%), insulin (-55.64%), and insulin resistance (-56.31%) compared to the 50 mg/kg dose, bringing these parameters closer to normal control values." (PMID 40229885, 2025). "In normoglycaemic patients without insulin resistance, insulin is produced only following a meal that causes blood sugar to rise." (PMID 38778593, 2025). "Also, the univariate ANCOVA test results showed a significant difference between groups after 12 weeks of training in body weight, BMI, fat percentage, fasting blood glucose, insulin, and insulin resistance while adjusting for the pretraining." (PMID 40123054, 2025). "On one hand, periodontal disease triggers the release of inflammatory cytokines, such as interleukin-6 (IL-6) and tumor necrosis factor-alpha (TNF-α), which impair insulin signaling pathways, resulting in increased insulin resistance and poor glycemic control in diabetic patients." (PMID 40283848, 2025). "Insulin resistance is a multifaceted pathophysiological condition, characterized by diminished bodily response to insulin, leading to increased blood glucose levels, which ultimately may manifest as T2DM and metabolic syndrome." (PMID 40141412, 2025). "In states of insulin resistance, impaired insulin signaling in endothelial cells, along with elevated levels of insulin and aldosterone, lead to reduced bioavailability of nitric oxide and vascular stiffness, thereby promoting the onset and progression of ASCVD." (PMID 40486823, 2025). "In healthy pregnancies, insulin secretion rises to adapt to the increased insulin resistance." (PMID 40722699, 2025). "Correlations between SCTT and umbilical cord blood insulin, C-peptide, and the Homeostasis Model Assessment of Insulin Resistance (HOMA-IR) have been reported across diverse populations, suggesting a robust physiological relationship between fetal fat accretion and in utero hyperinsulinemia." (PMID 40870841, 2025). "The reduction in circulating SCFAs, showcased in our results, may contribute significantly to the decrease in insulin sensitivity and the development of insulin resistance, a major clinical feature of PCOS." (PMID 40438215, 2025). "While insulin secretion defects are the primary mechanism in CFRD pathophysiology, insulin resistance may contribute as an additional risk factor." (PMID 41300682, 2025). "Several factors contribute to insulin resistance, including defects in the insulin signaling cascade, the inhibition of the cascade through pro-inflammatory pathways, and even insulin resistance induced by fatty acids due to lipid accumulation in the liver and muscles." (PMID 40429815, 2025). "During hepatic insulin resistance, it has been hypothesized that insulin activates SREBP1c, and due to hyperinsulinemia, this pathway is overactivated, leading to excessive DNL." (PMID 40985048, 2025). "In addition, Astragalus polysaccharide has been proven to improve insulin resistance and glucose metabolism through various signaling pathways, and it can also protect islet beta cells and improve insulin sensitivity." (PMID 40650120, 2025). "Also, genetic targeting of c-Jun-N-terminal kinases protects against insulin resistance and the switch towards an M1-like state in mice, as they play a role in polarization and interfere with insulin signaling." (PMID 41472730, 2025). "The presented meta-analysis of randomized controlled trials aimed to analyze the effectiveess of fenugreek (Trigonella foenum-graecum) on fasting blood glucose (FBG), 2-hr postprandial glucose (2hPPG), Hemoglobin A1c (HbA1c), Insulin and Insulin resistance (HOMA-IR)." (PMID 41509111, 2025).
Insulin resistance (continued). "In healthy adults, inhibition of gastrointestinal sweet taste receptors with lactisole—a compound known to block sweet taste perception —was found to modify insulin responses during oral glucose intake, leading to elevated plasma insulin levels and inducing mild, temporary insulin resistance." (PMID 40873447, 2025). "However, the physiologic interpretation of the reduction in hepatic glucose uptake (GU) during the gold-standard measurement of insulin sensitivity, hyperinsulinemic euglycemic clamp, in insulin resistance is unclear." (PMID 40391305, 2025). "Excessive activation of additional inflammatory variables, such as elevated neutrophil, IL-6, and CRP levels, as well as immune response abnormalities, such as decreases in lymphocyte, monocyte, CD4+, and CD8+ T-cell counts, results in insufficient insulin production and systemic insulin resistance." (PMID 40469441, 2025). "In addition, reduced systemic levels of pro-inflammatory cytokines and mediators such as TNF-α and C-reactive protein lead to improvements in insulin resistance and insulin signaling." (PMID 40299548, 2025). "Insulin resistance (IR) is a prevalent metabolic disturbance characterized by a diminished biological response of peripheral tissues—particularly skeletal muscle, liver, and adipose tissue—to circulating insulin." (PMID 40981168, 2025). "Insulin resistance leads to elevated insulin levels in the blood." (PMID 40703555, 2025). "However, WP supplementation increased fasting insulin and homeostatic model assessment of insulin resistance." (PMID 41228181, 2025). "However, insulin resistance was markedly higher in obese children, as indicated by elevated fasting insulin and HOMA-IR levels." (PMID 40641901, 2025). "Moreover, anthocyanins stimulate β cells in the rodent pancreas to secrete insulin and improve glucose tolerance and insulin resistance." (PMID 40535170, 2025). "Insulin resistance occurs due to loss of sensitivity of its receptor, which causes reduction in the formation of GLUT, reduces utilization of glucose, which promotes the level of blood insulin in GD and type 2 diabetes." (PMID 40126146, 2025). "GiL extract can also provide additional anti-diabetic benefits, such as anti-inflammation, anti-insulin resistance, and insulin mimetic activity, the inhibition of α-amylase and α-glucosidase actions, a reduction in intestinal glucose absorption, and anti-adipocyte differentiation." (PMID 40298831, 2025). "A study administering a 5-day dietary challenge mimicking Western diets (high fat, high-calorie diet) showed that healthy South Asians exhibited increased fasting glucose, insulin and insulin resistance compared to age and BMI matched-white European counterparts." (PMID 40410155, 2025). "Insulin resistance and defects in insulin secretion present before pregnancy or in early pregnancy." (PMID 40361947, 2025). "Additionally, fasting serum glucose and insulin levels were measured to calculate the homeostatic model assessment for insulin resistance (HOMA-IR) at the end of the treatment period." (PMID 40722894, 2025). "These epigenetic changes could exacerbate insulin resistance by altering the expression of key genes involved in adipogenesis and insulin signaling." (PMID 41036090, 2025). "There is a range of basal insulin levels within a population, and hyperinsulinemia, or elevated circulating insulin without hypoglycemia, is often detected when there is clinically defined insulin resistance." (PMID 40013621, 2025). "Furthermore, studies have shown that hepatocyte injury triggers the release of hepatokines, which can induce peripheral insulin resistance by interfering with insulin signaling in skeletal muscle and adipose tissue." (PMID 40880520, 2025).
Insulin resistance (continued). "Furthermore, chemerin, vaspin, and apelin exhibit anti-inflammatory, insulin-sensitizing, and anti-apoptotic effects, whereas resistin and visfatin contribute to insulin resistance, ER stress, and inflammatory cytokine production, exacerbating hepatic injury." (PMID 40243565, 2025). "We hypothesize that 5-HT inhibition could restore normal insulin signaling and glucose uptake in skeletal muscles through the 5-HT receptor 2b (Htr2b), thereby alleviating obesity-induced insulin resistance." (PMID 40451926, 2025). "It has been proposed in the past that insulin resistance may adaptively change in response to levels of insulin or glucose." (PMID 38895272, 2025). "In patients with gestational diabetes mellitus, MI metabolic disorders were shown to be potentially exacerbated by aberrant elevation of MIOX activity, resulting in MI depletion and attenuation of insulin signaling, thereby promoting insulin resistance development." (PMID 41020866, 2025). "Furthermore, a notable interaction between p.Asn318Ser and insulin resistance was observed in normoglycemic individuals, suggesting that dyslipidemia is more severe in p.Asn318Ser carriers with decreased insulin sensitivity." (PMID 40747209, 2025). "Conversely, caloric restriction improves insulin sensitivity, measured by Homeostatic Model Assessment for Insulin Resistance (HOMA-IR) or clamp techniques, in both cohorts with and without obesity, thereby reducing FFA flux to hepatocytes and enabling partial reversal of lipid overload." (PMID 41153720, 2025). "Furthermore, it can improve insulin sensitivity and glycemic control by attenuating postprandial blood glucose and insulin excursions, benefiting individuals with insulin resistance." (PMID 40626223, 2025). "Furthermore, increased cellular insulin resistance leads to hyperglycemia and decreased cellular sensitivity to insulin." (PMID 41464936, 2025). "Similarly, in the liver, these impairments exacerbate lipotoxicity and insulin resistance, while in the pancreas, dysregulated autophagy affects insulin secretion and pancreatic β-cell viability." (PMID 40366502, 2025). "Additionally, research involving HFD-fed hamsters showed that CUR enhanced insulin sensitivity, as evidenced by reduced insulin resistance index values." (PMID 40376699, 2025). "Although insulin is crucial for neuronal metabolism and mitochondrial function, increasing peripheral insulin levels by consuming high amounts of glucose can lead to hyperinsulinemia and insulin resistance." (PMID 41009493, 2025). "Insulin resistance may be exacerbated by anomalies in the insulin receptor, diminished insulin production, and disruptions in the signaling cascade, impeding the body’s ability to utilize insulin efficiently." (PMID 40226620, 2025). "Additionally, insulin resistance, accompanied by obesity, suppresses insulin from inhibiting hormone-sensitive lipase activity in adipose tissue, thereby promoting the breakdown of stored fat and releasing it as FFAs into the bloodstream." (PMID 40278408, 2025). "Understanding how insulin signalling integrates the molecular mechanisms of GSV translocation is essential for determining the steps affected in insulin resistance, which may facilitate the development of novel targeted therapies." (PMID 40806697, 2025). "Resistance to the metabolic actions of insulin is called as insulin resistance (IR)." (PMID 39471069, 2025). "Insulin plays a critical role in bone metabolism; consequently, insulin resistance may lead to diminished bone formation and increased bone resorption, thereby heightening the risk of osteoporosis." (PMID 40260282, 2025). "Insulin resistance, which is a condition affecting the body's overall ability to process glucose and lipids, is defined by the presence of elevated insulin levels (hyperinsulinemia), high blood sugar (hyperglycemia), and increased blood lipids (hyperlipidemia)." (PMID 40416818, 2025).
Insulin resistance (continued). "Compensatory insulin hypersecretion, in response to insulin resistance, may lead to pancreatic β-cell dysfunction and a decline in insulin secretion, thus leading to the development of prediabetes and DM." (PMID 39859181, 2025). "However, insulin resistance remained an essential component, defined as a fasting insulin level above the 75th percentile for the population." (PMID 40217852, 2025). "Further investigations into the absorption of SPs in the intestine, accelerated hypersecretion of insulin, and conversion of glucose to energy in the livers of SP rats are needed to clarify the molecular mechanisms by which SPs induce insulin resistance and glucose intolerance." (PMID 40074175, 2025). "Insulin resistance is characterized by insulin resistance and insufficient insulin secretion, and patients may have symptoms such as obesity and pre-meal hypoglycemia." (PMID 40362436, 2025). "Additionally, the kidney’s role in sodium transport and blood pressure regulation is influenced by insulin signaling pathways, further complicating its involvement in insulin resistance." (PMID 40698245, 2025). "Transplanting the gut microbiota of mice in the semaglutide intervention group to recipient mice can reduce fasting blood glucose and insulin levels, improve insulin resistance, reduce lipid accumulation in white adipose tissue and liver, and regulate levels of lipid metabolism-related factors." (PMID 40552153, 2025). "Similarly, GLP-1 plays another key role in the development of T2DM, including regulation of glucose homeostasis, insulin secretion, and alteration of insulin resistance." (PMID 40190404, 2025). "Persistent insulin resistance enhances pancreatic insulin secretion, leading to hyperinsulinemia." (PMID 41272918, 2025). "Similarly, a higher CRF was associated with a lower risk of the MetS-WC (β = -0.59, p = 0.009), lower insulin resistance (HOMA-IR: β = -1.42, p = 0.019) and with increased insulin sensitivity (MATSUDA: β = 0.99, p = 0.017)." (PMID 41276872, 2025). "A study proposed that decreased fasting insulin levels might play a crucial role in alleviating insulin resistance and inflammation in cartilage tissues." (PMID 40761349, 2025). "However, in critically ill patients, abnormalities in the insulin signaling pathway often lead to the occurrence of insulin resistance." (PMID 40475963, 2025). "In AD and obesity, brain insulin resistance denotes reduced neuronal and glial responsiveness to insulin, characterized by impaired IRS-1/PI3K-AKT signaling, increased inhibitory serine phosphorylation of IRS-1, and downstream overactivation of GSK3β that favors tau phosphorylation." (PMID 41155642, 2025). "We observed similar patterns in the validation cohort LLD While being younger as compared to participants in cluster H, LLD participants in cluster U had significantly (p < 0.05) higher BMI, triglycerides, CRP and insulin levels and insulin resistance, while presenting lower HDL_c." (PMID 39834614, 2025). "Insulin resistance is fundamentally a state of diminished insulin sensitivity." (PMID 39136514, 2025). "Given that insulin resistance and hyperinsulinemia are recognized as major contributors to DN development, improved insulin function may partially explain the observed inverse association between magnesium intake and DN risk." (PMID 40717994, 2025). "Crucially, nobiletin combats insulin resistance, protects pancreatic β-cell function, enhances insulin secretion, and modulates key signaling pathways (including AMPK, PI3K/AKT, PPARs, NF-κB, and circadian regulators like Bmal1/RORs) to improve glucose and lipid homeostasis." (PMID 41155643, 2025). "The activity of SGLT2 inhibitors is independent of insulin status, meaning their efficacy is not diminished by insulin resistance or absolute insulin deficiency, making them suitable for use in both Type 2 and Type 1 diabetes." (PMID 40430150, 2025).
Insulin resistance (continued). "These inflammatory markers interfere with insulin signaling, contributing to insulin resistance." (PMID 40641901, 2025). "An elevated TyG index is indicative of insulin resistance, and dysregulation of the insulin signaling pathway may contribute to blood–brain barrier (BBB) endothelial alterations by affecting tight junction proteins, thereby increasing BBB permeability." (PMID 40271183, 2025). "There is evidence that, along with the autoimmune attack, insulin resistance is present in T1D, supporting the concept that changes in insulin sensitivity may play a role in the progression of this disease." (PMID 39998445, 2025). "Notably, “insulin resistance” involves both decreased and preserved insulin actions in a tissue-specific manner." (PMID 40868889, 2025). "HIIT was linked to slight improvements in insulin resistance in obese men, though its impact on glucose and insulin regulation was not significant." (PMID 40005372, 2025). "They suggested that adults with NF1 could have low levels of leptin and resistin and high levels of adiponectin which could decrease insulin resistance and increase insulin sensitivity." (PMID 40376359, 2025). "Consistent with previous findings of elevated fasting glucose levels in the O3-exposed mice, these results suggest that chronic O3 exposure induces glucose intolerance, which can be mediated by insulin resistance, impairment of insulin sensitivity, and β-cell dysfunction." (PMID 40863931, 2025). "A breakdown in insulin signaling under metabolic stress can lead to persistent systemic hyperinsulinemia and insulin resistance, which is characterized as a reduction in the impact of insulin on important target tissues (including adipose tissue, liver, and skeletal muscle)." (PMID 40565979, 2025). "While the pathogenesis of GDM remains unclear, it is evident that beta-cell dysfunction and the failure of insulin secretion to compensate for insulin resistance induced by pregnancy are significant contributing factors." (PMID 41333061, 2025). "Similarly, elevated levels of IL-6 are noted in instances of obesity and type 2 diabetes and are linked to chronic inflammation that ultimately results in the disruption of insulin signaling, thereby exacerbating insulin resistance." (PMID 40149935, 2025). "Since reduced adiponectin levels cause insulin resistance in mice,our data suggest that HIRA may regulate insulin response/sensitivity, at least in part, by controlling Adipoq expression." (PMID 40196683, 2025). "However, the HEC test is expensive and complex to perform, and thus, indirect methods, such as the homeostasis model assessment index for insulin resistance (HOMA-IR) or fasting plasma insulin are frequently used, because they are easier to perform." (PMID 40560922, 2025). "These inflammatory factors may exacerbate insulin resistance by interfering with insulin signaling pathways." (PMID 40607227, 2025). "It activates insulin signaling in skeletal muscle cells and has the capacity to decrease inflammation in adipose tissue and monocytes, thereby leading to the alleviation of insulin resistance and T2DM." (PMID 39980831, 2025). "The study findings suggest that M. charantia may be used to improve insulin sensitivity and reduce insulin resistance, thereby improving hyperglycaemia in patients with prediabetes and T2D." (PMID 41280283, 2025). "The hypoglycemic effect of quercetin may be related to its ability to increase insulin secretion, improve insulin resistance, and inhibit apoptosis." (PMID 40273147, 2025). "Insulin resistance in adipose and skeletal muscle cells may result from a defect in insulin signalling, abnormal GLUT4 trafficking, or a combination of both." (PMID 40806697, 2025). "However, in case of hepatic insulin resistance and corresponding too low insulin infusion rate insulin sensitivity is underestimated." (PMID 40249709, 2025).